NLRP3 (NLR family pyrin domain containing 3)
Diseases named in the same sentence as NLRP3 in open-access papers (continued):
Sharing a sentence is not in itself a finding about the gene and the disease.
Obesity (continued). "Similarly, NLRP3 gene deletion also ameliorated hepatic steatosis and inflammation in models of diet-induced obesity." (PMID 36817440, 2023). "NLRP3 may also be activated in macrophages by several obesity-related factors, including elevated levels of ceramides, reactive oxygen species (ROS), ATP, and mitochondrial dysfunction." (PMID 37446154, 2023). "Moreover, obesity activates inflammasomes such as NOD-like receptor family pyrin domain-containing 3 (NLRP3), which is involved in diseases such as non-alcoholic fatty liver disease (NAFLD), Type 2 diabetes, and chronic kidney disease (CKD))." (PMID 37214340, 2023). "In any case, the NLRP3 inflammasome represents an interesting starting point for the therapy of low-grade inflammation in obesity and the availability of clinical antagonists of IL-1β opens new possibilities for the therapy of T2DM and cardiovascular diseases in the context of obesity." (PMID 37239938, 2023). "A possible explanation for the effects on the Sertoli cell and sperm parameters is that severe obesity may trigger the activation of the NLRP3 inflammasome complex, leading to the production of the proinflammatory cytokines, IL-1β and IL-18." (PMID 36675601, 2023). "Given that obesity-related increase in NLRP3 inflammasome activation is a predominant regulator of IL-1β production and decreased health span, we next tested whether SPARC gain of function impacts the inflammasome." (PMID 37781916, 2023). "In addition, obesity disrupts mitochondrial integrity, leading to the release of reactive oxygen species, which triggers the formation of NLRP3 inflammasome complexes." (PMID 35571243, 2022). "Our data provide evidence that NLRP3 promotes obesity-related spermatogenesis impairment." (PMID 35915511, 2022). "We propose, that [Ca2+]ex-induced, CaSR mediated NLRP3 activation of macrophages in obesity is a relevant trigger of local and systemic inflammation, which might be targeted therapeutically." (PMID 35931812, 2022). "MLFE may have potential therapeutic value in treating obesity and obesity-related complications, and NLRP3 might be a promising target in the fight against obesity wounds since it may promote the early healing of wounds." (PMID 35992142, 2022). "In AT in obesity, CaSR expression has been reported to be involved in AT inflammation, since it is upregulated on adipocytes in response to inflammatory cytokines and triggers their proinflammatory response by activating the NLRP3 inflammasome." (PMID 35931812, 2022). "A potential target of these adipokines could be the NLRP3 inflammasome, a critical component of the innate immune system, the harmful pro-inflammatory effect of which affects both adipose and lung tissue in obesity." (PMID 35806353, 2022). "Particularly, over expression of NLRP3 inflammasome is now identified as a key player in the development of numerous inflammatory and autoimmune diseases which include atherosclerosis, neuro-degenerative diseases, obesity and T2DM." (PMID 35966098, 2022). "As expected, we also found that NLRP3 deficiency could prevent obesity-related spermatogenesis impairment and preserve the function of the BTB, demonstrating a maladaptive role for NLRP3 during the development of obesity-related spermatogenesis impairment." (PMID 35915511, 2022). "Emerging evidence has indicated that the NLRP3 inflammasome, a critical component of the innate immune system, could play a key role in promoting lung disease in obesity." (PMID 35806353, 2022). "Hence, implying that obesity induced insulin resistance (IR) and NLRP3 inflammasome activation are interconnected." (PMID 35966098, 2022). "Another therapeutic target could be the NLRP3 inflammasome, whose activity is upstream of a pro-inflammatory cytokine cascade with harmful effects that affects both adipose tissue and lungs in obesity." (PMID 35806353, 2022). "Targeting NLRP3 may represent a promising strategy for treating obesity-related spermatogenesis impairment." (PMID 35915511, 2022).
Obesity (continued). "In this study, the reduction of the NLRP3 inflammasome and the CASP-1 proteins by exercise training, supports the idea that the NLRP3 inflammasome detects danger signals associated with obesity and contributes to obesity-induced inflammation." (PMID 36358820, 2022). "Genetic ablation of NLRP3 prevents HF-induced obesity, obesity-induced ATM, and inflammation." (PMID 36142842, 2022). "The expression of fibroblast growth factor-2, an adipokine, is enhanced in the adipose tissue and during adipocyte differentiation in mice with high-fat-diet-induced obesity and activates the NLRP3 inflammasome, while exercise training can effectively reverse this situation." (PMID 36232938, 2022). "Similarly, platelets from subjects with IR and obesity were found to have an upregulated expression of mRNA for IL-1β and NLRP3 inflammasome." (PMID 35563363, 2022). "Accordingly, mice deficient in NLRP3 do not develop obesity and insulin resistance while fed with HFD." (PMID 36555392, 2022). "Understanding the underlying molecular mechanism of how the AMPK/NF-κB pathway and related NLRP3 inflammasome affect obesity and obesity-induced inflammation might lead to preventive strategy for obesity-mediated metabolic diseases." (PMID 36142842, 2022). "It has been showed that NLRP3 expression and activity are involved in adipose tissue dysfunction and inflammation in obesity, in addition to their involvement in Treg/Th17 imbalance and with lung health in patients with COPD, asthma, rheumatoid lung disease, and COVID-19." (PMID 35806353, 2022). "Because of the activation of fatty acids and ceramides, the lipotoxic environment of obesity may activate the inflammasome NLRP3." (PMID 35456284, 2022). "To investigate the potential role of NLRP3 in the pathological processes of obesity-related impairment of spermatogenesis, we first examined whether the NLRP3 expression levels were altered in the testes of obese mice." (PMID 35915511, 2022). "Nucleotide-binding oligomerization domain-like receptor with a pyrin domain 3 (NLRP3) is expressed in SCs, but the role of NLRP3 in the pathological process of obesity-induced male infertility remains unclear." (PMID 35915511, 2022). "In silicosis, the NLRP3 inflammasome is activated in AMs by phagocytosis of silica particles; in obesity the NLRP3 inflammasome can be activated by factors released by stressed adipocytes and through activation of pathogen recognition receptors (PRRs) of AT macrophages." (PMID 34976743, 2022). "Previous studies have recognized that the elevation of palmitate in the context of obesity may induce NLRP3 inflammasome activation in macrophages, leading to the overproduction of inflammatory cytokines and subsequent insulin resistance in mice." (PMID 36483560, 2022). "Thus, in obesity, NLRP3, through lipotoxic signals, such as free cholesterol and ceramides, causes an accelerated age-related thymic involution, leading to decreased T cell diversity with reduced naïve T cells and increased effector-memory T cells." (PMID 34685542, 2021). "Obesity itself also facilitates assembly of the NLRP3 inflammasome in adipose tissue macrophages, which could induce macrophage‐mediated T cell activation and IFN‐γ release." (PMID 34459122, 2021). "Moreover, NLRP3 inflammasome activation in the ovaries after early obesity contrasted with its activation exclusively during late obesity in the liver." (PMID 34805147, 2021). "Therefore, the ratio of mature caspase-1 and the level of PPARγ can be represented as an “NLRP3-accelerating index” in obesity." (PMID 33500734, 2021). "Conversely, in late obesity, immune-mediated response in the ovary mainly comprises the infiltration of immune cells and mediation of structural reorganization, independent from the activation of NLRP3 inflammasome." (PMID 34805147, 2021).
Obesity (continued). "Furthermore, calorie restriction, exercise and weight loss through bariatric surgery have been associated with lower gene expression of NLRP3 and IL-1β, thus suggesting that obesity-induced MetS and NLRP3 inflammasome activity are interrelated." (PMID 34362072, 2021). "Moreover, TLR4-NF-κB can regulate the activation of NLRP3 inflammatory bodies and participate in various inflammatory diseases, such as hepatic lipid metabolism in obesity." (PMID 34760017, 2021). "However, the role of the NLRP3 inflammasome in IL-1β release through GSDMD pores during obesity-induced IR in skeletal muscle tissue remains unexplored." (PMID 34638553, 2021). "Considering the role of the NLRP3 inflammasome in inducing metabolic disorders, the inhibitory effect of licochalcone A on the NLRP3 inflammasome may mediate the blockade of high-fat diet-induced obesity and metabolic disorders by the compound." (PMID 33534121, 2021). "The downregulation of NLRP3 inflammasome activity in NAG-1 Tg mice may confer resistance against diet-induced obesity and improve insulin sensitivity." (PMID 34294853, 2021). "In this work, we address the hypothesis that during obesity-induced IR, there is an increase in the NLRP3 inflammasome complex, IL-1β, and GSDMD protein content in the skeletal muscle." (PMID 34638553, 2021). "Understanding the mechanisms involved in the regulation of NLRP3 inflammasome in adipose tissue may help in the development of specific inhibitors for the treatment and prevention of obesity-mediated metabolic diseases." (PMID 33435142, 2021). "NLRP3 activation impairs insulin sensitivity in dietary-induced obesity." (PMID 33435142, 2021). "In addition, in VAT of obese patients, NLRP3 inflammasome is upregulated and in vivo experiments showed that NLRP3 deficient mice are protected from HFD-induced obesity, suggesting a crucial role of inflammation in obesity." (PMID 35095876, 2021). "Obesity, as well as aging, triggers activation of the NLRP3 inflammasome." (PMID 34564326, 2021). "The NLRP3 inflammasome seems to act as a sensor for metabolic danger signals (endogenous DAMPs and PAMPs) that accumulate during obesity, including saturated free fatty acids (FFAs), ceramides, high levels of glucose, uric acid, and Islet Amyloid Polipeptyde (IAAP)." (PMID 33546399, 2021). "In 2010, Zhou and colleagues were the first researchers who indicated that the NLRP3 inflammasome may impact the regulation of adiposity and insulin sensitivity in the course of obesity." (PMID 34070553, 2021). "Indeed, NLRP3 inflammasome seems to play a critical role mostly in the initiation of inflammation in the ovaries in early obesity." (PMID 34805147, 2021). "NLRP3 is activated by saturated fatty acids such as palmitate and stearate, as well as free cholesterol and cholesterol crystals, and by oxidative stress, which is also known to be present in AT in obesity." (PMID 33418879, 2021). "What’s more, the inappropriate activation of the NLRP3 inflammasome could contribute to the onset and progression of various diseases, such as obesity, type 2 diabetes, inflammatory bowel disease, rheumatoid arthritis, liver fibrosis, Myocardial infarctions." (PMID 34266494, 2021). "MCC950, a specific inhibitor of NLRP3 inflammasome activation, has been recently used as a treatment for various NLRP3-related pathological models, including frontotemporal dementia, age-related metabolic syndrome, and obesity-induced insulin resistance." (PMID 34638553, 2021). "In other words, obesity promotes pyroptosis by enabling the release of the NLRP3 inflammasome, which may be related to OA progression." (PMID 33014529, 2020). "Additionally, visfatin was shown to mediate arterial inflammation and endothelial dysfunction during early stages of obesity, via an NLRP3 inflammasome dependent endothelial inflammatory response." (PMID 33182523, 2020).
Obesity (continued). "Additionally, in comparison to wild-type mice, NLRP3 knockout mice show substantial improvement in insulin sensitivity during a high-fat diet; this approach provides protection against obesity." (PMID 32012695, 2020). "Therefore, such DNA that accumulates during obesity is likely to contribute to obesity-mediated pathogenesis though the activation of NLRP3 as well." (PMID 33574823, 2020). "In addition, it is worth further exploring the beneficial effects of NLRP3 deactivators on adipose tissue inflammation and metabolic health during aging and obesity, yet their potential side effects on immunosuppression should also be considered." (PMID 32545355, 2020). "The reduction in the NLRP3 inflammasome and CASP-1 proteins by exercise training reinforces the idea that the NLRP3 inflammasome detects danger signals associated with obesity and contributes to obesity-induced inflammation." (PMID 32624568, 2020). "NLRP3-dependent IL-1β secretion has been shown to impair pancreatic beta cell function, adipocyte function, and insulin sensitivity, promoting the progression of obesity and insulin resistance." (PMID 32751530, 2020). "Recent studies suggest that pattern recognition receptors such as NLRP3 play a critical role in detecting obesity factors including cholesterol and dietary fatty acids, which may initiate an inflammatory response." (PMID 33167400, 2020). "Finally, the NLRP3 inflammasome was previously reported to promote obesity-mediated pathogenesis upon its activation by intracellular ceramide." (PMID 33574823, 2020). "Moreover, perturbations in the NLRP3 inflammasome could be associated with changes in gut microbiota, supporting the anti-inflammatory role of physical exercise because of its modulatory effect on gut microbiota composition and functionality in children with obesity." (PMID 32624568, 2020). "In a randomized, double-blind, placebo-controlled crossover trial (n = 11) we tested the hypothesis that acutely raising β-OHB by ingestion of exogenous ketones would attenuate NLRP3 activation in humans with obesity." (PMID 32209983, 2020). "We and others have suggested that NLRP3 inflammasome may be a missing link between obesity and cardiovascular and metabolic disorders, but the molecular pathways that mediate these interactions are intensively debated and remain to be fully defined." (PMID 33273482, 2020). "Furthermore, activation of NLRP3 has been shown to be critical to the development of obesity-induced insulin resistance in mice and humans." (PMID 32209983, 2020). "In acid sphingomyelinase (ASM) knockout mice, less caspase-1 and IL-1β production are observed, which suggests that the ASM may participate in the activation of NLRP3 inflammasome during the development of obesity-related kidney disease." (PMID 32175320, 2020). "The imbalance of lysosome-dependent sphingolipid metabolism may induce NLRP3 inflammasome activation, leading to podocyte injury and glomerular sclerosis during obesity." (PMID 32106480, 2020). "However, the deletion of the ASM gene totally blocked NLRP3 inflammasome activation and glomerulosclerosis during obesity." (PMID 32106480, 2020). "Therefore, the primary purpose of this study was to investigate the effect of exogenous ketone ingestion on markers of NLRP3 activation in individuals with obesity." (PMID 32209983, 2020). "Next, we decided to test the hypothesis of that the absence NLRP3 inflammasome may be selectively affecting our OVAbil model since it has been previously reported that NLRP3 is involved in the development of obesity and liver steatosis." (PMID 32716024, 2020). "Thus, it seems that NLRP3 deficiency markedly attenuated the increase in ceramide species during obesity pointing to a role for ceramides as a mechanism for NLRP3-driven inflammation during metabolic stress." (PMID 33273482, 2020).
Obesity (continued). "NLRP3 (gene encoding NALP3: NACHT, LRR and PYD domain-containing protein 3) is a NLR highly expressed in ATMs that forms a crown-like structure around senescent adipocytes upon diet-induced obesity." (PMID 32785109, 2020). "However, we cannot exclude that NLRP3 inflammasomes modulate obesity-induced effects on the myocardium through the systemic effects of ceramides-induced inflammation." (PMID 33273482, 2020). "Ablation of NLRP3 enhances insulin signaling in a mouse model of obesity." (PMID 31461911, 2019). "The present study was designed to explore this hypothesis by examining Nlrp3 and ASC (Pycard) deficient mice in a model of obesity induced cardiac remodeling." (PMID 31379826, 2019). "We found that the cardiac hypertrophic response to obesity was independent of the NLRP3 inflammasome, while deficiency of NLRP3 and ASC blunted the concentric form of cardiac remodeling and the impairment of diastolic function seen in obese WT mice." (PMID 31379826, 2019). "Increasing evidence points to the involvement of the NLRP3 inflammasome in obesity-induced inflammation and insulin resistance, and we hypothesized that it also could play a role in the development of obesity induced cardiac alterations." (PMID 31379826, 2019). "Thus, in line with our findings that NLRP3 and ASC (Pycard) deficient mice were protected against obesity-induced metabolic dysfunction, these mice were also able to suppress development of hepatic steatosis during HFD." (PMID 31379826, 2019). "Obesity promotes the initiation of NLRP3 inflammasome formation in diabetic patients." (PMID 31835423, 2019). "In addition, the NLRP3 inflammasome expression levels have been shown to be related with obesity and type II diabetes." (PMID 31319552, 2019). "In the development of obesity in mice induced by a high-fat diet, pretreatment with casein hydrolysate showed that NLRP3 inflammasome-mediated IL-1β secretion in adipose tissue could be attenuated." (PMID 31174550, 2019). "Based on these previous studies, we hypothesized that the NLRP3 inflammasome plays a role in the development of cardiac dysfunction and remodeling during diet-induced obesity." (PMID 31379826, 2019). "Based on the recent findings that NLRP3-associated inflammasome is upregulated in T2DM patients and instigates obesity-induced inflammation in insulin resistance, we have started to evaluate whether plasma mtDNA is oxidatively damaged in T2DM patients." (PMID 31600210, 2019). "In addition, NLRP3 inflammasome has been reported to be a critical component in the pathogenesis of metabolic disorders such as obesity and type 2 diabetes." (PMID 29434227, 2018). "However, in specific conditions such as obesity, the chronic activation of NLRP3 can promote tumor cell growth, migration and invasion." (PMID 30619282, 2018). "In particular, NLRP3 appears to be involved in obesity-induced inflammation and Type 2 diabetes." (PMID 29170442, 2017). "Furthermore, SFAs were recently identified as triggers of the NLRP3 inflammasome in macrophages; additionally, they increase the secretion of IL-1β and IL-18, both of which play a role in the development of obesity-induced insulin resistance." (PMID 29258239, 2017). "Moreover, in obese asthma mice, IL-1β mRNA and NLRP3 mRNA expression were significantly increased compared with the asthma and obesity groups (P<0.05)." (PMID 29160418, 2017). "Moreover, NLRP3 inflammasome is also critical in the development of allergic airway inflammation and in the pathophysiology of obesity." (PMID 29160418, 2017). "Also, it has been shown that ceramides can activate the NLRP3 inflammasome in obesity-induced inflammation." (PMID 28829355, 2017). "Obesity may induce NLRP3-dependent caspase-1 activation and thus pyroptosis and the proinflammatory response in hypertrophic adipocytes." (PMID 29104591, 2017).